LILRB3 (leukocyte immunoglobulin like receptor B3)
Diseases named in the same sentence as LILRB3 in open-access papers:
LILRB3 is named in the same sentence as 44 diseases in open-access papers, as found by Europe PMC text mining. Sharing a sentence is not in itself a finding about the gene and the disease. The quoted sentences say what the papers report.
leukemia (5 papers, 2022 to 2024). A malignant (clonal) hematologic disorder, involving hematopoietic stem cells and characterized by the presence of primitive or atypical myeloid or lymphoid cells in the bone marrow and the blood. "LILRB3 blockade decreased the AML disease burden of LILRB3 expressing MLL-AF9 leukemia in immunocompetent mice and an AML PDX in humanized mice." (PMID 39696628, 2024). "Differential gene expression analysis found that many upregulated genes in the C2 subtype were associated with increased leukemia cell survival, proliferation, and drug resistance, such as S100A8, S100A9, LILRB3, KLF4, LST1, and ITGB2." (PMID 37691822, 2023). "LILRB3 has been found to be expressed in leukaemia and a few solid cancers, such as hepatocellular and colorectal cancers, and its expression is associated with a poor OS." (PMID 38022598, 2023). "Cell proliferation in human leukemia cell lines is suppressed when LILRB3 expression is inhibited." (PMID 38486250, 2024). "One study reported that 5.4% of HSC transplant recipients had LILRB3-targeting antibodies that may promote a graft-versus-leukemia effect against LILRB3-expressing leukemic cells, proposing LILRB3 as a viable target for antibody-based immunotherapies." (PMID 35076022, 2022). "These patients also expressed LILRB3 on leukemic cells, proposing LILRB3 as a GVH and graft-versus-leukaemia target." (PMID 38022598, 2023).
acute myeloid leukemia (2 papers, 2025). Acute myeloid leukemia (AML) is a group of neoplasms arising from precursor cells committed to the myeloid cell-line differentiation. "Another study showed that CLPs-miR-103a-2-5p suppressed the growth and led to programmed cell death in acute myeloid leukemia (AML) cells by specifically interacting with LILRB3 and modulating the Nrf2/HO-1 pathway." (PMID 40403492, 2025).
Autoimmunity (2 papers, 2020 to 2023). The occurrence of an immune reaction against the organism's own cells or tissues. "Another study showed that GA acts as a ligand for PIR-B, LILRB2 and LILRB3 on MDSCs, whose activation promotes Th2 immunity and the release of cytokines that suppress autoimmunity." (PMID 38022598, 2023). "This demonstrates the capacity of LILRB3 to exert profound immunosuppressive effects that may be exploited in therapeutic settings, such as autoimmunity and transplantation, where transient induction of immune tolerance will be beneficial." (PMID 32870822, 2020).
cardiac hypertrophy (2 papers, 2022 to 2023). "Collectively, our results delineated that ANGPTL8 ameliorated the development of pathological cardiac hypertrophy via the LILRB3-Akt/GSK3β signaling cascade." (PMID 35851270, 2022). "In summary, ANGPTL8, which binds to LILRB3, negatively regulates the development of pathological cardiac hypertrophy by inhibiting Akt/GSK3β activity." (PMID 35851270, 2022).
lymphoma (2 papers, 2019 to 2020). A malignant (clonal) proliferation of B- lymphocytes or T- lymphocytes which involves the lymph nodes, bone marrow and/or extranodal sites. "LILRB1 (also known as CD85J, ILT2, LIR1, and MIR7) and LILRB3 (CD85A, ILT5, LIR3, and HL9) are widely expressed on malignant cells of hematologic malignancies, such as AML, B cell leukemia/lymphoma, and T cell leukemia, where they intrinsically promote tumor progression." (PMID 31186046, 2019). "Accordingly, LILRB3-treated tumor-bearing humanized mice subsequently succumbed to disease with high tumor burden, whereas isotype control–treated mice readily rejected the lymphoma cells without morbidity." (PMID 32870822, 2020).
autoimmune hepatitis (1 paper, 2019). Hepatitis caused by autoantibodies. "Autoimmunity in these individuals could plausibly have been ascribed to predicted-damaging RFP variants in genes with strong associations to lupus (IRF5, LILRB3) or autoimmune hepatitis (C4A)." (PMID 31307400, 2019).
breast carcinoma (1 paper, 2023). "IL4R promotes breast cancer growth and LILRB3 can block antitumor immune activation." (PMID 36980301, 2023).
Burkitt lymphoma (1 paper, 2016). A rare form of malignant mature B-cell non-Hodgkin lymphoma. "The EBV positive and negative Burkitt's lymphoma B cell lines Daudi and BJAB, the embryonic kidney cell line HEK293T and an HLA-G transfected EBV transformed B cell line 721.221 did not induce the expression of GFP in the LILRB3 reporter 2B4 cells." (PMID 26769854, 2016).
chronic graft versus host disease (1 paper, 2025). Chronic graft versus host disease (GVHD) is a complication that can occur after a stem cell or bone marrow transplant in which the newly transplanted donor cells attack the transplant recipient's body. "In another study that investigated lncRNA expression in chronic graft-versus-host disease, three lncRNAs (NONHSAT142151, NONHSAT040475 and FR118417) were found to strongly correlate with the expression of mRNAs related to the BCR signaling pathway (BTK, CD72, DAPP1, LILRB3, NFKBIE, RASGRP3)." (PMID 39940921, 2025).
clear cell renal cell carcinoma (1 paper, 2025). "LILRA1, LILRA2, LILRA5, LILRB1, LILRB2, and LILRB3 are differentially expressed across several cancer types, including lung squamous cell carcinoma, lung adenocarcinoma, papillary renal cell carcinoma, and clear cell renal cell carcinoma, suggesting a potential pan-cancer role for LILR family genes." (PMID 40843931, 2025).
colorectal cancer (1 paper, 2023). A primary or metastatic malignant neoplasm that affects the colon or rectum. "Interestingly, ectopic expression of LILRB3 on colorectal cancer cells associates with lower TILs and its high expression within the TME correlates with worse OS." (PMID 38022598, 2023).
glioma (1 paper, 2025). A benign or malignant brain and spinal cord tumor that arises from glial cells (astrocytes, oligodendrocytes, ependymal cells). "indicates that LILRB3 is predominantly expressed on monocyte-derived tumor-associated macrophages (Mo-TAMs) in gliomas, with high LILRB3 expression serving as an independent negative prognostic factor across various glioma grades." (PMID 40843931, 2025).
lepromatous leprosy (1 paper, 2016). A chronic communicable infection which is a principal or polar form of leprosy. "However, LILRA3 together with LILRB5 and LILRB3 were found to be over expressed in lesions of patients with lepromatous leprosy, where their overexpression was thought to correspond to an ineffective immune response." (PMID 26908331, 2016).
liver cancer (1 paper, 2022). An epithelial or non-epithelial malignant neoplasm that arises from the liver. "Our study revealed that the mRNA expression of LILRB1, LILRB2, LILRB3, and LILRB5 was downregulated, while compared with normal tissues, the mRNA expression of LILRB4 was upregulated in liver cancer tissues." (PMID 35321724, 2022).
melanoma (1 paper, 2025). A malignant, usually aggressive tumor composed of atypical, neoplastic melanocytes. "Notably, therapeutic blockade of LILRB3 successfully inhibited immunosuppressive activity of MDSC from melanoma patients." (PMID 40860159, 2025).
multiple sclerosis (1 paper, 2020). A progressive autoimmune disorder affecting the central nervous system resulting in demyelination. "A recent study investigating the mode of action of glatiramer acetate (Copaxone), a peptide-based drug licensed in the late 1990s, used to treat patients with the relapsing-remitting form of multiple sclerosis that ameliorates autoimmunity, identified LILRB2 and LILRB3 as potential ligands." (PMID 32870822, 2020).
myeloid leukemia (1 paper, 2024). A clonal proliferation of myeloid cells and their precursors in the bone marrow, peripheral blood, and spleen. "It has been reported that certain cells of myeloid leukemia, B lymphoid leukemia, and myeloma express LILRB3." (PMID 38486250, 2024).
prostate carcinoma (1 paper, 2025). A carcinoma that arises from epithelial cells of the prostate gland. "Genome-wide association studies (GWAS) have revealed that several LILRs are associated with diseases, such as Takayasu arteritis (LILRB3/LILRA3) and prostate cancer (LILRA3)." (PMID 40260241, 2025).
renal carcinoma (1 paper, 2025). A carcinoma arising from the epithelium of the renal parenchyma or the renal pelvis. "Ultimately, this will provide a theoretical basis for a deeper understanding of the immunological and clinical significance of LILRB3 in renal cancer and the development of novel immunotherapeutic strategies." (PMID 40843931, 2025). "To investigate the impact of LILRB3 gene silencing on the proliferation and migration abilities of ccRCC cells, we established LILRB3 knockdown renal cancer cell lines." (PMID 40843931, 2025).
rheumatoid arthritis (1 paper, 2021). A chronic, systemic autoimmune disorder characterized by inflammation in the synovial membranes and articular surfaces. "LILRB2, LILRB3 and LILRA2 were highly upregulated in synovial tissues from rheumatoid arthritis (RA) patients." (PMID 34594332, 2021).
Sepsis (1 paper, 2022). Sepsis is defined as life-threatening organ dysfunction caused by a dysregulated host response to infection. "Furthermore, treatment with a peptide that antagonized paired Ig-like receptor B (PIR-B), the murine LILRB ortholog, augmented survival of septic mice with pulmonary pathology, implicating LILRB3 as a potential target to treat sepsis." (PMID 35076022, 2022).
tumor (17 papers, 2016 to 2025). "Further elucidation of the precise mechanisms underlying LILRB3-mediated immunomodulation is imperative for the development of targeted therapeutic approaches aimed at counteracting tumour progression and enhancing anti-cancer immune responses." (PMID 40385641, 2025). "Flow cytometry of cells stained with recombinant, soluble LILRB3 (allele LILRB3*12) fused to the Fc portion of human IgG1 bound to glandular epithelial tumour cells, confirming the pattern of 2B4 activation." (PMID 26769854, 2016). "We used RT-qPCR to validate the differential expression of the five genes most strongly linked to inflammation and tumor immune responses: chemokine Ccl7, cytokine Csf2/GM-CSF, cytokine receptors Il4r and Il18r1, and inhibitor of antitumor immunity through antigen presentation Lilrb3." (PMID 36980301, 2023). "The immune regulatory effects induced by LILRB3 activation and its mechanisms within the tumor microenvironment require further clarification, which will necessitate the use of animal models and more mechanistic studies." (PMID 40843931, 2025). "Ligation of LILRB3 on human monocytes results in functional suppression of myeloid cells in vitro and promotion of tumour growth in vivo." (PMID 40385641, 2025). "Secondly, the sample size for immunohistochemical validation of LILRB3 expression differences between tumor tissues and adjacent normal tissues was limited, which to some extent affects the statistical power and generalizability of our conclusions." (PMID 40843931, 2025). "LILRB3 expression was significantly higher in CRC versus normal colorectal epithelium and associated with LN metastasis, advanced tumor stages and reduced survival." (PMID 40860159, 2025). "LILRB3 appears to exert a regulatory effect on PD-L1 expression in ccRCC, potentially facilitating tumor cells’ evasion of immune surveillance." (PMID 40843931, 2025). "In conclusion, the current findings demonstrate that miR-103a-2-5p serves as a tumor suppressor targeting LILRB3 to inhibit proliferation and induce apoptosis in AML cells." (PMID 38486250, 2024). "Although, regarded as an orphan receptor, recent findings suggest that LILRB3 interacts with ANGPTL2 and 5, complement components, and cytokeratin-associated proteins exposed on necrotic tumour cells and bacteria such as S. aureus." (PMID 38022598, 2023). "LILRB3 mAb treatment induced tolerance in vivo and enabled successful engraftment of allogeneic tumour cells in a humanised mouse model." (PMID 38022598, 2023). "The immune microenvironment was characterized by moderate infiltration of M2-like tumor-associated macrophages (TMAs) with positivity of CD163, CSF1R, CD85A (LILRB3), and PD-L1; moderate PD-1 positive T cells, and low FOXP3 regulatory T lymphocytes (Tregs)." (PMID 36975733, 2023). "The LILRB3 cluster also contained CXCL2; the CXCL2-CXCR2 axis helps in the recruitment of tumor-associated neutrophils (TANs)." (PMID 36134663, 2022). "Co-staining with the DAPI nuclear stain indicated LILRB3-Fc binding to dead epithelial tumour cells, suggesting that a LILRB3 ligand is exposed on these cells following necrosis." (PMID 26769854, 2016). "LILRB3 reporter cells were co-seeded and cultured with a wide range of human tumour cell lines including those derived from B cells and epithelial cells." (PMID 26769854, 2016). "LILRB3 plays a crucial role in regulating tumor growth and proliferation." (PMID 40843931, 2025). "This suggests that LILRB3 may confer a mechanism by which tumour cells can subvert immune surveillance and resist therapeutic interventions." (PMID 40385641, 2025). "It was hypothesized that the engagement of LILRB3 on tumour cells with their ligands initiates inhibitory signalling cascades, thereby enabling immune evasion." (PMID 40385641, 2025). "Moreover, a recent study identified tumour-derived galactin-4 and galactin-7 as potential ligands for LILRB3, that result in suppression of TAMs upon binding to LILRB3." (PMID 40385641, 2025).
tumor (continued). "Three more variants in KRTAP4-11, NBPF20 and LILRB3 were found in four primary tumour samples, each from patients without recurrence, while being absent in all primary tumours of patients with recurrences and the local/distant relapses." (PMID 35008243, 2021). "The binding of LILRB3 to dead epithelial tumour cells was assessed further by staining cells with recombinant Fc fusion molecules following treatment with H2O2 or NaN3 (to induce necrosis), staurosporine (STS, to induce apoptosis) or subjected to mechanical damage by repeated trituration." (PMID 26769854, 2016). "Still, alteration of myeloid cells via LILRB3 activation could affect tumor immunology." (PMID 38503797, 2024). "LILRB3 as well as LILRA6 (> 90% extracellular homology) have been found to interact with cytokeratin-associated proteins on necrotic glandular epithelial cells, which may enhance tumour immune-evasion." (PMID 38022598, 2023). "The LILRB3/A6 interaction with these cells may be exploitable in an anti-tumour immunotherapy." (PMID 26769854, 2016). "Although the ligand for LILRB3 is not so clear, some studies suggested that LILRB3 was associated with cytokeratin-associated proteins exposed to necrotic cancer cells and might be involved in altering the immune responses within the tumor microenvironment." (PMID 35321724, 2022). "These interactions could be blocked by a specific LILRB3 mAb, which retarded tumour growth in galectin-4 expressing MC38 tumour bearing preclinical models." (PMID 40385641, 2025). "MiR-103a-2-5p serves as a tumor suppressor that could inhibit AML cell proliferation and promote their apoptosis by downregulating LILRB3 expression, suppressing the Nrf2/HO-1 axis, and reducing the ratio of GSH/ROS." (PMID 38486250, 2024). "To determine whether LILRB3 modulates the tumor growth and cell proliferation of AML by interacting with miRNAs, we looked up bioinformatics websites to predict the target miRNAs of LILRB3." (PMID 38486250, 2024). "The balance of signals transmitted by inhibitory LILRB3 and activating LILRA6 might therefore determine whether an immune response is initiated to the dead tumour cell, thereby to influence the wider immune response within the tumour microenvironment." (PMID 26769854, 2016). "Since LILRB3 and LILRA6 genes are highly polymorphic the interaction may influence an individual's immune response to tumours." (PMID 26769854, 2016). "LILRB3 has not yet been extensively studied with respect to tumour immune-evasion and development." (PMID 38022598, 2023). "The balance of signals transmitted by paired LILRB3/LILRA6 receptors might therefore determine whether an immune response was triggered to the necrotic tumor cell, thereby leading to a wider immune response within the tumor microenvironment." (PMID 33795528, 2021). "The LILRB3 protein is thought to ameliorate inflammatory responses and limit autoreactivity by binding to MHC class I molecules on antigen-presenting cells and might confer a survival advantage when upregulated, and the PDGFL protein has tumor suppression properties." (PMID 35328091, 2022). "Epithelial cells cultured from four subjects tested induced expression of GFP by the LILRB3 reporter, suggesting that expression of the ligand of LILRB3 is not specific to tumour cells and may also be expressed on cells of glandular epithelial origin, whether normal or transformed." (PMID 26769854, 2016).
cancer (9 papers, 2015 to 2025). A tumor composed of atypical neoplastic, often pleomorphic cells that invade other tissues. "Although typically regarded as an orphan receptor, earlier studies suggest that LILRB3 may associate with cytokeratin-associated proteins such as those exposed on necrotic cancer cells." (PMID 32870822, 2020). "Therefore, LILRB3 is an attractive diagnostic and therapeutic target for cancer." (PMID 38486250, 2024). "In summary, LILRB3 exhibits the potential to modulate immune responses and foster immune escape mechanisms in cancer." (PMID 40385641, 2025). "LILRB3 exerts an inhibitory effect on immune effector cells, thus facilitating the evasion of cancer cells from their effects." (PMID 40385641, 2025). "LILRB3 was up-regulated in a variety of cancers, including AML, and was significantly increased in AML patients compared to normal people, based on GEPIA data." (PMID 38486250, 2024). "Recent founding proved the importance of LILRB3 in the cancer context, leading to the rapid development of anti-LILRB3 antagonist antibodies and chimeric-antigen receptor T-cells (CAR T-cells) to boost the anti-tumoral response." (PMID 39010891, 2024). "Notably, LILRB3 expression has also been shown ectopically on some cancer cells, including colorectal cancer cells." (PMID 40385641, 2025). "For instance, activation of LILRB3 was recently reported to induce NF-κB pathway in cancer cells." (PMID 39010891, 2024). "Disruption of the interaction between LILRB3 and its potential ligand on necrotic cancer cells may, thus, inhibit such intrinsic tumor immunoevasion strategies." (PMID 35076022, 2022). "LILRB3, a member of the leukocyte immunoglobulin-like receptor B (LILRB) family, has immunosuppressive functions and directly regulates cancer development, which indicates that LILRB3 is an attractive target for cancer diagnosis and therapy." (PMID 38486250, 2024). "LILRB3, a member of the LILRB family, might play two different functions in the biology of cancer, which could directly regulate cancer development and have immune inhibitory functions." (PMID 38486250, 2024).
infection (1 paper, 2022). The state of being infected such as from the introduction of a foreign agent such as serum, vaccine, antigenic substance or organism. "First, CD33+ MDSCs were purified using FACsort from donor PBMCs and treated with mab-B2 and LILRB3-specific mab-B3, followed 1 day later by infection with Mtb and growth assay over 7 days." (PMID 35757769, 2022).
LILRB3 also shares sentences with these, for which no sentence is quoted: coronary artery disease (2 papers); acute myocardial infarction (1); angina (1); asthma (1); atherosclerosis (1); B cell lymphoma (1); cerebrovascular diseases (1); fatty liver (1); hair diseases (1); hematologic malignancies (1); HIV-1 infection (1); kidney (1); lung adenocarcinoma (1); lung squamous cell carcinoma (1); lupus (1); Miscarriage (1); myeloma (1); papillary renal cell carcinoma (1); sarcoidosis (1); Takayasu arteritis (1).